APOE (apolipoprotein E)
Diseases named in the same sentence as APOE in open-access papers (continued):
Sharing a sentence is not in itself a finding about the gene and the disease.
tumor (continued). "Consistent with our earlier work on active astrocytes at the tumor edge, the accumulation of APOE in this region may reflect the altered metabolic state of reactive astrocytes." (PMID 40745073, 2026). "Immunofluorescence (IF) staining showed a distinct APOE signal at the tumor border." (PMID 40745073, 2026). "In addition, the APOE signal was slightly higher in the tumor edge than in the tumor core in the GL261 model." (PMID 40745073, 2026). "Immunofluorescence (IF) staining showed that APOE was accumulated at the tumor edge." (PMID 40745073, 2026). "In addition, ISH staining of APOE mRNA revealed that the RNA spots were sparsely distributed within tumor core, with strong signal accumulation in a few scattered cells, indicating highly localized expression." (PMID 40745073, 2026). "We partitioned tumour cells into two groups based on APOE expression, acknowledging that the zero‐inflation inherent to single‐cell data might introduce some degree of error." (PMID 39810624, 2025). "Moreover, consistent with the in vitro results, APOE knockdown obviously weakened the tumor growth promoted by FTO overexpression, as reflected by tumor weight and tumor volume." (PMID 39990672, 2025). "These analyses suggested that tumor cells might promote differentiation of CD34+ Fbs into APOE+ Fbs and MMP3+ Fbs in D‐TGCT, turning “mild” fibroblast clusters into “aggressive” ones." (PMID 40126353, 2025). "Other compounds were demonstrated the suppressive effect on MDSCs viability and accumulation in tumor tissue, including apolipoprotein E (ApoE), LXRβ agonists, such as GW3965 and RGX-104, a novel therapeutic peptide-Fc fusion protein that targeted the S100A family proteins." (PMID 40050933, 2025). "This indicates that the dysregulation of APOE+ macrophage marker genes may participate in tumour immune modulation, cellular structural maintenance and stress response mechanisms in LUAD." (PMID 40736341, 2025). "In addition, we found APOE+ macrophage gather accumulate around tumor borders, as well as abundant TGF-β signaling." (PMID 40303328, 2025). "They further suggested that APOE might contribute to a metastasis‐inhibiting tumour microenvironment by modulating inflammatory factors and anticancer T cells." (PMID 39810624, 2025). "This suggests that APOE + CTSZ + TAMs may utilize the CXCL16 signaling pathway to recruit Tregs to tumor sites, thereby further exacerbating the immunosuppressive TME." (PMID 40191203, 2025). "Furthermore, APOE expression was also positively correlated with tumor TNM stages, and patients with high Macro_APOE cell signatures in the TCGA AEG cohort showed a poor prognosis." (PMID 40963562, 2025). "APOE− tumor cells may promote tumor growth by interacting with dendritic cells and CD4+ T cells via CD99‐ rather than CD6‐regulated signaling." (PMID 39810624, 2025). "Recent studies have shown that APOE can also participate in the regulation of tumor progression." (PMID 41390817, 2025). "Additionally, SPP1 signaling from malignant cells appeared to recruit APOE+ macrophages to tumor margins, and promotes macrophage polarization into APOE+ M2-like macrophages." (PMID 40303328, 2025). "This reveals a dual role for ApoE: on one hand, it might promote tumour growth, while on the other, it has the potential to enhance immune responses against tumours." (PMID 40662483, 2025). "Specifically, APOE+ tumour cells were involved in the CD6‐driven network, along with immune cells." (PMID 39810624, 2025). "One study found that IGF2BP2 may work to promote tumor growth in PTC via interactions with APOE mRNA and the IL-6/JAK2/STAT3 pathway." (PMID 40243425, 2025). "Additionally, an analysis of tumor tissue from a PCa tissue array disclosed an inverse correlation between APOE and AR protein expression." (PMID 40365288, 2025). "Collectively, these data suggest that APOE may influence the tumour microenvironment and progression through multiple pathways." (PMID 39810624, 2025).
tumor (continued). "Furthermore, APOE partakes in an array of biological processes related to tumour progression, such as the augmentation of tumour cell growth, the initiation of metastasis, and the promotion of angiogenesis." (PMID 40437660, 2025). "In addition to physiological aging, it has been found that apolipoprotein E (APOE) secreted by tumor cells induces a subset of senescent neutrophils expressing the triggering receptor expressed on myeloid cells 2 (TREM2), which correlates with poor prognosis." (PMID 40860134, 2025). "Notably, the enrichment of collagen and integrin interactions (e.g., COL1A1_ITGA1) further indicates that APOE+ macrophages organize the tumor stroma elements to facilitate tumor progression and immune evasion." (PMID 40303328, 2025). "The identification of these TREM2/APOE/C1Q-positive macrophages not only offers a potential prognostic biomarker for ccRCC recurrence but also presents a promising target for therapeutic strategies aimed at preventing tumor relapse." (PMID 40083710, 2025). "Additionally, while our findings suggest that tumor-intrinsic APOE plays a role in shaping the tumor microenvironment, the precise mechanism through which APOE regulates PD-L1 expression and influences immune modulation requires further investigation." (PMID 40365288, 2025). "Interestingly, when we placed APOE+ Fbs at the center of the network, we also observed strong interaction between MP3 tumor cells and APOE+ Fbs." (PMID 40126353, 2025). "Exosomes have a crucial function in facilitating the spread of metastatic castration-resistant prostate cancer (CRPC) by transporting proteins such as APOE, LRG1, and ITIH that are directly implicated in tumor growth and the formation of secondary tumors in the bones." (PMID 39187523, 2024). "However, in this case, the probability of tumor formation was calculated to be similar in the Nude, Skh-hr2, and Skh-hr2 + ApoE models." (PMID 39456640, 2024). "Notably, the expression levels of APOE, BGN, C1QB, and BST2 were found to correlate with cancer genomic atlas data, and were implicated in tumor immune infiltration." (PMID 39650066, 2024). "Similarly, the sum of H-scores for apoE pronounced trend in the K-M survival curves, with shorter OS in those with higher apoE expression in tumour tissue." (PMID 38976030, 2024). "Both CD14+APOE+ cells and MMP7+ tumour cells were associated with worse survival." (PMID 39187937, 2024). "To address this hypothesis, we first conducted expression plots of CTHRC1, GREM1, SPP1, and APOE in the TCGA cohort, which were all significantly enriched in tumor samples versus control." (PMID 39075108, 2024). "Targeted interventions that modulate these pathways could potentially reduce tumor growth and improve treatment outcomes for APOE ε2 carriers." (PMID 39763652, 2024). "Overall, APOE gene polymorphisms influence lipid metabolism in LUAD patients, characterized by reduced HDL levels and elevated TG, which provide essential energy and biosynthetic precursors for tumor cell proliferation." (PMID 39763652, 2024). "Furthermore, single-cell RNA sequencing (scRNA-seq) identified a subset of apolipoprotein E gene (ApoE+) PMN-MDSCs that act as an important source of PD-L1 in the tumor microenvironment of ICC and helps suppress response to immune checkpoint blockade." (PMID 38474232, 2024). "The primary outcome variable of the study was cancer development, without differentiating between specific types of malignancies, however, the analysis of APOE gene polymorphism and tumor risk did not include the Chinese population." (PMID 39763652, 2024). "Furthermore, APOE, APOC1, C1QA, C1QB, and NUPR1 are indicative markers of variations in the infiltration of tumor-associated macrophages (TAM), where TAM infiltration is known to be associated with unfavorable survival outcomes in solid tumors." (PMID 38783355, 2024). "Tumor-associated macrophages (TAMs) that express MMP9 and APOE were also present in this cluster." (PMID 39639005, 2024).
tumor (continued). "C1Q+TREM2+APOE+ TAMs detected in tumour stroma were proven to correlate with cancer recurrence." (PMID 38303024, 2024). "The precise mechanisms through which APOE genotypes influence malignant tumor progression remain unclear." (PMID 39763652, 2024). "Besides, the effects of the amount of apoE protein in tumour tissues on the OS of patients has been discussed in different cancer types before." (PMID 38976030, 2024). "There is a significant relationship between ApoE and the tumor microenvironment (TME)." (PMID 38349474, 2024). "Apolipoprotein E (ApoE) secreted by M2-EV worsens the immunogenicity of tumor cells." (PMID 39896803, 2024). "Additionally, neutrophils isolated from lungs within metastatic 4T1 tumor cells show higher expression of ApoE and S100A4 compared with neutrophils from the lungs of mice without tumors." (PMID 39695088, 2024). "The proposed mechanisms through which APOE accelerated cancer is in relation with intracellular adhesion and junctions, thereby decreasing cell contact inhibition and polarizing normal cells to tumor cells through the PI3K/Akt/mTOR pathway." (PMID 38067270, 2023). "In addition, the role of apoE in tumor progression has been revealed, although it has been controversial." (PMID 37310025, 2023). "Apolipoprotein E (apoE) has previously been reported to play vital roles in tumor progression." (PMID 37310025, 2023). "Apolipoprotein E (ApoE) expression in tumor stroma influences immune suppression." (PMID 37958351, 2023). "In addition, APOE has been reported to be highly expressed in a variety of tumor types and to promote cancer progression." (PMID 37251536, 2023). "CD74‐MIF signaling plays an important role in immunosuppression, indicating that Macro_APOE/CTSZ may recruit Treg to infiltrate tumor tissue to inhibit antitumor immune responses." (PMID 36587392, 2023). "Next, we attempted to study how APOE+ macrophages enhanced MVI of tumor cells." (PMID 37853415, 2023). "Furthermore, based on the crosstalk analysis in this study, we identified that APOC1+APOE+ macrophages were involved in the establishing of the metastatic immune microenvironment by interacting with tumor and stromal cell." (PMID 36709495, 2023). "In addition, the spatial characterization of APOE+ APOC1+ macrophages in microenvironment of primary tumor and metastatic lymph node were evaluated by multiplex IF staining." (PMID 36709495, 2023). "Our previous research has shown that SPP1+ TAMs and APOE+CYSZ+ TAMs are involved in regulating tumor invasion phenotypes and glycolysis in lung cancer and the recruitment of T regulatory (Treg) cells and formation of an immunosuppressive TME in colorectal cancer (CRC), respectively." (PMID 38002057, 2023). "However, the precise interplay by which APOE works in the tumor microenvironment needs further study." (PMID 38054821, 2023). "ApoE activation has been linked to enhanced MDSC apoptosis and consequent tumor regression." (PMID 37529351, 2023). "Recent studies showed that ApoE is involved in the pathogenesis of infection and tumor development." (PMID 37529351, 2023). "Interestingly, the decoration of the liposomes with ApoE improved the transfection of tumor cells with the therapeutic gene." (PMID 36986734, 2023). "We speculated that the opposite effects of APOE in tumor progression might be attributed to the complexity of metabolic characteristics and the tumor microenvironment in different cancer types." (PMID 37310025, 2023). "Furthermore, the highly expressed DEGs of fibroblasts in LNM included immune-related genes (CCL21, CCL19, CCL2, and MYC), metabolism-related genes (STEAP4, FABP4, DPT, and APOE), and genes related to tumor proliferation and progression (RGS, CCN, and MYC)." (PMID 37221625, 2023). "These contradictory findings suggest that whether APOE plays a tumor-promoting or -suppressing role may be tumor-type-dependent and context-dependent." (PMID 37958351, 2023).
tumor (continued). "The mean fluorescence intensity (MFI) of DiR was higher in Nano-reshaper group than that of pLIGHT@CaCP group in T cells, macrophages, DCs and tumor cells, indicating that the decoration of ApoE peptide enhanced the targeting ability of nanoparticles to these cells." (PMID 36702831, 2023). "ApoE also protects tumors by suppressing tumor cell immunogenicity." (PMID 36341364, 2022). "However, the immune mediated effect was not as apparent in the lrp8-/- mice, as activation of immune pathway and cellular RNA transcripts were not universally increased liked that observed in the complete apoE knock out tumor/mouse model." (PMID 36341364, 2022). "APOE is an oncomarker of tumor-infiltrating macrophages in mouse models and human tumors." (PMID 36147474, 2022). "Furthermore, reduced FTO in combination with m6A modification of APOE can modulate the IL-6/JAK2/STAT3 signaling pathway to promote tumor glycolysis, thereby aggravating the progression of PTC." (PMID 36506554, 2022). "In several human cancers, APOE gene expression is significantly higher in cancer tissue than in adjacent non-cancer tissue and higher levels of tumor APOE are associated with metastasis." (PMID 36341364, 2022). "Additionally, the activation of the LXR/APOE axis was shown to elicit robust antitumor responses in various tumor models and human tumor cell lineages." (PMID 36131916, 2022). "To determine if knocking out apoE in tumor cells induced immunogenicity, we vaccinated wild type and apoE-/- mice or wild type and lrp8-/- mice with WT B16 or apoE-/- B16 tumor cells and CTLA4 Ab and then collected splenocytes from these vaccinated mice 6 days later." (PMID 36341364, 2022). "We employ CRISPR gene editing to assess the tumor-intrinsic effects of ApoE." (PMID 36341364, 2022). "One possibility is that the statistical significance in decreased levels of APOE phosphorylation at the S147 locus might serve as signals of dysregulated functional patterns in tumor samples." (PMID 37304007, 2022). "Hence, a further analysis of the innate and adaptive immune responses (including possibly depletion strategies to validate the model) is required to fully understand the implications of apoE in tumor immunity." (PMID 36341364, 2022). "This work shows that tumor immunity can be restored and enhanced by targeting apoE." (PMID 36341364, 2022). "In general, we observed APOC1, APOE, C1QB and NURP1, which may reflect differential abundance of tumor-associated infiltration of macrophages (TAM)." (PMID 36250636, 2022). "Then, matched tumor and normal samples were immunohistochemically stained to verify whether the expression of APOE protein in the Shanghai cohort was consistent with the TCGA database and The HPA database." (PMID 35371313, 2022). "Complete deletion of apoE in the tumor cells and in the host was most effective for inhibition of tumor growth, while apoE-/- B16 cells injected into WT mice, or WT B16 cells injected into apoE-/- mice or lrp8-/- mice partially suppressed tumor growth compared to control." (PMID 36341364, 2022). "Moreover, treatment by exploiting APOE inhibitor (αAPOE) was capable of curbing tumor development and fostering regression if in combination of αPD-1." (PMID 36147474, 2022). "The findings showed that APOE also promoted tumor growth through glycolysis in PTC." (PMID 35090515, 2022). "ApoE might strongly inhibit the proliferation of various cell types and influence angiogenesis, tumor cell growth, and metastasis by modulating the production of cytokines, growth factors, and other molecules." (PMID 35892323, 2022). "The regulation mechanism of APOE in vivo might be very complex, and we believe that Kemp Samantha B's study research fits in well with our research for APOE on tumor immunity." (PMID 36147474, 2022). "APOE modulates its effect on angiogenesis, tumor cell growth and metastasis induction in cancers." (PMID 35246549, 2022).
tumor (continued). "However, Tavazoie Masoud F's study showed that liver-X nuclear receptor (LXR) /ApoE activation therapy elicited robust anti-tumor responses and enhanced T cell activation during various immune-based therapies." (PMID 36147474, 2022). "As shown by the in vivo and in vitro results, PMs modified with the Aβ-CN peptide bound to ApoE efficiently and accumulated rapidly in the tumor tissues, which significantly improved cellular uptake efficiency on C6 cells and HUVECs and the rate of transport across the BBB and BBTB." (PMID 34963449, 2021). "Indeed, TAMs show high levels of gene expression enriched in the pathways which promote cell migration, angiogenesis, tumor progression, and inflammation (e.g., APOE and SPP1)." (PMID 33144684, 2021). "To investigate whether the APOE gene plays an oncogenic role in other tumours, we analysed its differential expression in normal tissues and in various tumours, through the GEPIA website." (PMID 33521130, 2021). "GSEA results showed that APOE was mainly enriched in fatty acid metabolism, and the regulation of ROS signaling pathways can regulate the body's metabolism and the microenvironment of tumor cells." (PMID 34873574, 2021). "However, the function of apoE in tumor cells is unclear as it has opposing effects in different cancers." (PMID 32306242, 2020). "When these apolipoproteins, including apoD, apoE and apoA-I, are present in cancer tissues, they tend to inhibit tumor growth, and these apolipoproteins may be used in the clinic as therapeutic targets." (PMID 32306242, 2020). "Furthermore, apoE hinders tumor cell multiplications by inhibiting the interactions among heparin-dependent cell matrixes." (PMID 32306242, 2020). "ApoD, apoE and apoA-I in mammary tissues inhibit tumor growth." (PMID 32306242, 2020). "Eventhough atherosclerogenesis is associated with tumor development, the role of ApoE in lung tumorigenesis and metastasis is not clear." (PMID 31275318, 2019). "However, a subset of genes up-regulated in microglia/tumor co-culture was found to be exclusively related to the concurrent presence of astrocytes (APOE, APOC2, HLA-DRA)." (PMID 31186414, 2019). "Taken together, our results suggest that ApoE itself may control tumor signaling and promote tumor development and metastasis, rather than control tumor growth through cholesterol metabolism." (PMID 31275318, 2019). "We analyzed whether ApoE and/or TREM-1 expression is associated with tumor development in lung tumor patients." (PMID 31275318, 2019). "Following these previous studies, we hypothesized that an increase of NK cell-mediated anti-tumor effect due to ApoE KO could be involved with TREM-1 expression." (PMID 31275318, 2019). "Altogether, these suggest that the regulation of lipid metabolism via ApoE expression may alter MDSCs function in the tumor milieu." (PMID 31275326, 2019). "These conflicting evidences indicate that the precise role of ApoE on tumor development could be affected by tumor environment factors." (PMID 31275318, 2019). "Also, histological analysis showed that lung metastatic tumor development was inhibited in the mice injected with ApoE-shRNA cells." (PMID 31275318, 2019). "Here we clarified that ApoE was primarily expressed in TAMs and tumor cells adjacent to TAMs in GC." (PMID 29567987, 2018). "Also, lesions in the ApoE−/− mice exhibited increased collagenous tissues, especially around the tumor lesions, indicated by Masson’s Trichrome stain." (PMID 29458390, 2018). "Different ApoE isoforms by binding to the LDL receptor could lead to various of biological behaviors for tumor, so the related research stratified by ApoE phenotypes is required." (PMID 30631342, 2018). "Likewise, the peritoneal cavity of ApoE−/− mice displayed ~ 2-fold and 2.64-fold increases in tumor number and weight, respectively." (PMID 29458390, 2018). "Compared to WT mice, ApoE−/− mice showed active ERK signaling in tumor lesions." (PMID 29458390, 2018).